MUC2 (mucin 2, oligomeric mucus/gel-forming)
Diseases named in the same sentence as MUC2 in open-access papers (continued):
Sharing a sentence is not in itself a finding about the gene and the disease.
prostate carcinoma (5 papers, 2004 to 2023). A carcinoma that arises from epithelial cells of the prostate gland. "For instance, MUC2 can be targeted by a bivalent conjugate vaccine previously studied for the treatment of resistant prostate cancers." (PMID 33400739, 2020). "The loss of hormone dependence in this prostate cancer xenograft model is therefore marked by irreversible histological alterations, mucinous or neuro-endocrine, associated with an expression of secretory MUC2, MUC5B and MUC6, independent of the histological differentiation subtype." (PMID 14760390, 2004). "Regarding secreted mucins, MUC2 epitopes were not expressed in normal prostatic tissue except near the utriculum, but were expressed in prostate cancer." (PMID 14760390, 2004).
rectal cancer (5 papers, 2007 to 2023). A primary or metastatic malignant neoplasm that affects the rectum. "This possibility was tested by comparing the distribution and frequency of the polymorphic MUC2 minisatellite alleles between controls and cancer patients with gastric, colon and rectal cancers." (PMID 18000536, 2007). "A case-control study was performed using PCR-based methods to score MUC2 minisatellite alleles in DNA from cancer-free controls and individuals with gastric, colon and rectal cancers." (PMID 18000536, 2007). "As a representative secreted mucin, MUC2 is mainly expressed in colorectal goblet cells and colon and rectal cancer cells." (PMID 37337182, 2023). "Collectively, these results imply that upregulated MUC2 expression is characterized by a more advanced clinical course and treatment resistance in rectal cancer patients undergoing CCRT, revealing the potential prognostic utility of MUC2 expression." (PMID 34300195, 2021). "In contrast, the epiregulin (EREG) gene was one of the top 200 genes that were co-downregulated with MUC2 (Spearman’s correlation: −0.379) and one of the favorable factors among rectal cancer patients receiving CCRT in our previous research." (PMID 34300195, 2021). "In this study, we illustrated that upregulated MUC2 expression is connected with aggressive clinicopathological features, and MUC2 can independently act as an unfavorable prognostic indicator and a druggable target for rectal cancer patients receiving CCRT." (PMID 34300195, 2021). "Impressively, the regenerating family member 4 (REG4) gene was identified as the fourth most significantly positively correlated gene with MUC2 (Spearman’s correlation: 0.776) and one of the predictive factors associated with CCRT resistance in rectal cancer in our previous study." (PMID 34300195, 2021). "In this study, we focused on genes related to maintenance of gastrointestinal epithelium (GO: 0030277) and identified mucin 2 (MUC2) as the most significantly upregulated gene correlated with CCRT resistance through a public rectal cancer transcriptome dataset (GSE35452)." (PMID 34300195, 2021). "Additionally, as almost all MCAs exhibit strong MUC2 expression regardless of tumor location, studies are needed to determine the link between MCAs and the poor prognosis for patients with rectal cancers and the association between MCAs and elevated levels of MUC2." (PMID 36916704, 2023). "Nevertheless, the correlations of MUC2 expression with the clinical outcomes of nonmetastatic rectal cancer patients undergoing preoperative CCRT are not well understood." (PMID 34300195, 2021). "MUC2 immunoreactivity in CCRT nonresponsive rectal carcinoma was considerably higher than that in CCRT responsive rectal carcinoma." (PMID 34300195, 2021). "Since most patients in our cohort had nonmucinous rectal cancer, whether high MUC2 expression is correlated with multiple metastases and an inferior response to immunotherapy in nonmucinous rectal cancer needs further investigation." (PMID 34300195, 2021). "Our prior study of MUC1 and MUC2 in CRCs showed that MUC1 is an indicator of poor prognosis for Caucasian patients, but there is, for African American or Caucasian patients, no prognostic value for MUC2 when colon and rectal cancers along with MCAs and NMCAs are combined." (PMID 36916704, 2023).
Sepsis (5 papers, 2018 to 2023). Sepsis is defined as life-threatening organ dysfunction caused by a dysregulated host response to infection. "As bacterial presence in the circulation (septicaemia) is a hallmark of sepsis, we determined if bacteria could survive in the circulation of Muc2−/− better than Muc2+/+ to cause increased damage." (PMID 31980623, 2020). "Finally, Muc2−/− receiving Muc2+/+ bone marrow exhibited higher susceptibility towards LPS-induced sepsis and mortality than Muc2+/+ littermates receiving Muc2−/− bone marrow." (PMID 31980623, 2020). "Of note, Muc1 is increased considerably after infection, a finding that is in agreement with our observation that Muc1 and Muc2 genes were upregulated after induction of experimental sepsis." (PMID 32041659, 2020). "In studies on Muc2 knockout animals, increased intestinal permeability has been shown to trigger a cascade of events leading to secondary organ inflammation and translocation of bacterial metabolites and bacteria per se leading to sepsis." (PMID 36076974, 2022). "All of these results indicate that GPR109A maintains the expression of tight junction genes and MUC2 protein, and has a role in controlling the permeability of the intestine in CLP-induced sepsis in mice." (PMID 30271409, 2018).
urothelial carcinoma (5 papers, 2007 to 2023). A malignant neoplasm derived from the transitional epithelium of the urinary tract (urinary bladder, ureter, urethra, or renal pelvis). "It has also been seen that the expression of MUC2 is observed more frequently in low-grade urothelial carcinomas and correlates with a low pathological stage." (PMID 36674608, 2023). "One study found that the positive rates of MUC1 and MUC2 in urothelial carcinoma were 89.7% and 44.3%, respectively, and MUC1 expression was significantly correlated with tumor grade, while MUC2 was the opposite." (PMID 35879749, 2022). "In this case, the panel was immunopositive for Muc-2, CK7 and CK20 and immunonegative for CDX-2; this, together with the histological findings, characterized a mucus-secreting urothelial carcinoma." (PMID 18094900, 2007). "Normal urinary tract epithelial cells do not express MUC2 and MUC5, while MUC2 is expressed in 40% of urinary tract carcinomas." (PMID 32664169, 2020).
atrophic gastritis (4 papers, 2006 to 2020). "In this study, we showed that HFD feeding induces Cdx2 and Muc2 expression associated with increased leptin levels, suggesting the possibility that leptin acts to suppress cellular protection against gastric mucosal malignancies in the early stage of atrophic gastritis." (PMID 26839577, 2016). "Additionally, MUC2 expression had a close relationship with atrophic gastritis." (PMID 23937908, 2013). "Among studies that included pediatric patients, the expression of MUC5AC, MUC6 and MUC2 were all increased in patients with intestinal metaplasia, but no data was available for gastric atrophy." (PMID 33322136, 2020).
Barrett's metaplasia (4 papers, 2008 to 2020). "Particularly MUC2 expression in Barrett's metaplasia is considered to indicate a higher risk for carcinoma." (PMID 18405344, 2008). "The presence of MUC2 in Barrett's metaplasia (goblet cells) is a feature of cellular differentiation because secretory mucins are normally produced by highly differentiated cells." (PMID 19272137, 2009). "MUC2 immunoexpression in Barrett's metaplasia was restricted to goblet cells, a pattern specific to normal rat and human colonic epithelium, implying that the mucin in goblet cells of Barrett's metaplasia is similar if not identical to the native intestinal mucosa." (PMID 19272137, 2009).
colon adenoma (4 papers, 2010 to 2025). An adenoma that arises from the colon. "Experiments in mice have shown that the loss of Muc2 can lead to the spontaneous formation of colonic adenomas." (PMID 41301470, 2025). "The complete loss or deletion of Muc4 in AMC mice was associated with a significant loss of Muc2 in the colon adenoma compared to normal mice." (PMID 35255004, 2022). "However, in many colonic adenomas and adenocarcinomas, MUC2 expression is diminished or even lost, exposing the intestinal lumen to inflammatory and tumor-promoting factors." (PMID 41301470, 2025). "MUC2 expression is seen in colon adenomas but in nonmucinous CRCs, MUC2 is reduced or lost during progression to adenocarcinoma." (PMID 28640835, 2017).
COVID-19 (4 papers, 2021 to 2025). A disease caused by infection with severe acute respiratory syndrome coronavirus 2. "In our study, mice transplanted with intestinal faecal microbiota from critically ill COVID-19 patients exhibited impaired intestinal epithelial barriers, disrupted integrity, reduced ZO-1 expression and decreased Muc2 levels." (PMID 40960868, 2025). "Compared with healthy controls and the mild non–COVID-19 group, expression of MUC2 mRNA was significantly altered in the critically ill patients with COVID and those with mild COVID-19." (PMID 34448730, 2021). "By using the same approach, we also showed that age and mRNA expression of MUC1, MUC2, MUC4, MUC6, MUC13, MUC16, and MUC20 were the most accurate variables associated with the presence of COVID-19 among symptomatic patients (AUCROC = 91.8%; sensitivity: 90.6%; specificity: 93.3%)." (PMID 34448730, 2021). "A strong positive correlation was also seen between MUC1 and MUC2 mRNA expression and between MUC16 and MUC20 mRNA expression and specifically in the mild COVID-19 patient group." (PMID 34448730, 2021). "MUC1, MUC2, MUC4, MUC16, and MUC20 mRNA expression strongly correlated with COVID-19 severity, of which MUC1 and MUC20 mRNA expression also associated significantly with age and MUC16 and MUC20 mRNA expression with sex." (PMID 34448730, 2021).
cyst (4 papers, 2018 to 2025). A sac-like closed membranous structure that may be empty or contain fluid or amorphous material. "All mutations were heterozygous, or present in a fraction of the TEC cells, and except for MUC2 were unique for one cyst." (PMID 32163234, 2020). "Histologic and cyst fluid biomarkers for high-risk IPMN, including KRAS, GNAS, and MUC1/MUC2/MUC4/MUC5A, will be used in future decision making about treatment." (PMID 33145018, 2020).
ductal adenocarcinoma (4 papers, 2010 to 2023). "Both membrane-bound (MUC1, MUC3, MUC4) and secreted mucins (MUC2, MUC5AC, MUC5B, MUC6) are upregulated in ductal adenocarcinoma of the breast." (PMID 30682816, 2019). "None of the ILCs and only a minority of invasive ductal carcinomas (IDCs) in the previous studies revealed MUC2 expression." (PMID 20550696, 2010).
esophageal adenocarcinoma (4 papers, 2008 to 2024). A malignant tumor with glandular differentiation arising predominantly from Barrett mucosa in the lower third of the esophagus. "A more detailed understanding of the precise mechanisms by which bile acids induce MUC2 could also facilitate the development of chemopreventive strategies to diminish the risk of carcinogenesis and metastasis, particularly in esophageal adenocarcinoma." (PMID 19014523, 2008). "A previous report has shown that bile acids (specifically deoxycholic acid) induced Muc2 overexpression in human esophageal adenocarcinoma cells through the activation of NF-κB transcription." (PMID 39446273, 2024). "In the current study, we sought to determine the effects of bile acids on MUC2 gene expression in esophageal adenocarcinoma cells and the molecular mechanisms involved." (PMID 19014523, 2008). "We therefore assessed the effect of NF-κB on expression of MUC2 induced by DCA in SEG-1 esophageal adenocarcinoma cells." (PMID 19014523, 2008). "We find that bile acids induce MUC2 expression in human esophageal adenocarcinoma cells at the level of transcription through a process that involves protein kinase C (PKC)-dependent activation of Nuclear factor-κB (NF-κB), primarily a MAP kinase-independent." (PMID 19014523, 2008). "Deoxycholic acid induced MUC2 overexpression in human esophageal adenocarcinoma cells by activation of Nuclear factor-κB transcription through a process involving PKC-dependent but not PKA, independent of activation of MAP kinase." (PMID 19014523, 2008). "Although regulations of MUC1 and MUC4 mucin genes by bile acids, such as DCA, CDCA and TCA, in human oesophageal cancer cells have been the thorough extensive study, the mechanisms responsible for regulation of MUC2 expression in the esophageal adenocarcinoma cells remain unknown." (PMID 19014523, 2008). "However, it is unclear whether induction of MUC2 by bile acids is mediated by PKC in esophageal adenocarcinoma cells." (PMID 19014523, 2008). "Bile acids has been reported to increase the secretion of MUC2 in esophageal cells, but MUC2 gene expression and the molecular events responsible for MUC2 gene expression were not studied in esophageal adenocarcinoma cells." (PMID 19014523, 2008). "To investigate the role of MAPK in the induction of MUC2 and NF-κB by DCA in esophageal adenocarcinoma cells, we examined phosphorylation of ERK1/2, JNK, P38 kinases and total ERK1/2, JNK, P38 kinases after treatment of SEG-1 cells with 100 μM DCA for 18 hours." (PMID 19014523, 2008). "In SEG-1 esophageal adenocarcinoma cells treated with DCA (100 μM) for 18 hours, the basal levels of MUC2 and NF-κB p65 proteins were decreased by treatment with 4 mmol/L aspirin, there was also partial inhibition of the bile acid-dependent induction of MUC2 and NF-κB p65." (PMID 19014523, 2008). "It is likely that these transcription factors activities may be also required for MUC2 expression in esophageal adenocarcinoma cells, but this has not yet been established." (PMID 19014523, 2008). "We conclude that treatment of human esophageal adenocarcinoma cells with DCA, up regulates MUC2 transcription by activation of NF-κB via PKC but not PKA, independent of MAP kinase." (PMID 19014523, 2008). "In contrast to previous work on MUC2 induction by PMA via the ERK cascade, we find that the induction of MUC2 by bile acid is independent of MAP kinases in SEG-1 esophageal adenocarcinoma cells." (PMID 19014523, 2008).
helminth infection (4 papers, 2012 to 2024). "In a study on IL-22-KO mice intestines, the increase in goblet cell number and muc2 expression was suppressed upon intestinal helminth infection." (PMID 34759916, 2021).
lung disease (4 papers, 2011 to 2016). "These were MUC1, MUC2, MUC5AC and MUC7 whose encoded proteins are of recognized importance in normal airway defense, and/or prior studies that indicate they play a role in diseases of the lung, and other inflammatory or malignant disease." (PMID 21998660, 2011). "Analysis of SNP data from candidate gene studies of MUC1, MUC2, and MUC5AC showed that none of the genotyped SNPs were highly associated with lung disease severity." (PMID 21998660, 2011).
mucinous colorectal adenocarcinoma (4 papers, 2019 to 2023). "Based on its molecular context, mucinous colorectal adenocarcinoma is associated with the overexpression of mucin 2 (MUC2) and mucin 5AC (MUC5AC) proteins." (PMID 30922401, 2019). "Mucinous colorectal adenocarcinoma is associated with higher positivity rate of MUC2 which produces mucin-2 (MUC2), a secreted protein that functions in the physiological processes of the gastrointestinal tract as a physical protection barrier." (PMID 30922401, 2019). "It was found that SCF/c-KIT signaling promotes the production of MUC2 and Mucinous Colorectal Adenocarcinoma (MCA) tumorigenesis by maintaining the expression of ATOH1." (PMID 38054820, 2023). "In addition, CEACAM5 was selected because it appears to be expressed in all primary tumors and generally at high levels and MUC2 because mucinous colorectal adenocarcinoma has a better prognosis than adenocarcinoma in general." (PMID 32049988, 2020). "However, concerning the differences between the gene expression levels in mucinous and non-mucinous colorectal adenocarcinomas, recent literatures suggest that MUC2 and MUC5AC could serve as potential targets for future treatments for mucinous colorectal adenocarcinoma." (PMID 30922401, 2019). "Overexpression of the MUC2 protein is one of the most evident molecular aberrations that distinct mucinous colorectal adenocarcinoma from its non-mucinous counterpart." (PMID 30922401, 2019).
mucinous ovarian cancer (4 papers, 2013 to 2024). An invasive malignant neoplasm that arises from the ovary and is characterized by the presence of malignant epithelial cells that contain intracytoplasmic mucin and may resemble the epithelial cells of the endocervix or gastrointestinal tract. "Regarding the cancer histotype, we observed that mucinous ovarian cancer most frequently expressed MUC2 molecules." (PMID 24324582, 2013). "The rate of MUC2 overexpression was significantly increased in mucinous ovarian cancer (p=0.002, χ2 test)." (PMID 24324582, 2013). "The authors found that MUC2 was expressed almost exclusively in mucinous ovarian cancers in the specimens they examined." (PMID 24324582, 2013). "The rate of MUC2 overexpression was 58.8% (10/17) in the mucinous ovarian cancer cases, which was significantly higher than the rates of 14.9% (10/67), 12.5% (1/8), 40% (2/5) and 0% (0/2) in the serous, endometrioid, clear cell and undifferentiated cancer cases, respectively." (PMID 24324582, 2013). "In line with the latest findings, Lee has recommended using a panel of CK7, CK20, CDX2, MUC2, 34βE12, and β-catenin to assist in the discrimination of urachal adenocarcinoma metastasis from primary ovarian mucinous carcinoma, and metastatic carcinoma from other organs." (PMID 23914849, 2013). "Genes such as MUC2, MUC5AC, MUC6, and MUC13, as well as the predominant intracellular presence of mucin, appear to be involved in the development and recurrence of mucinous ovarian carcinoma and can be used to differentiate between primary ovarian and metastatic lesions." (PMID 39598188, 2024).
ovarian tumor (4 papers, 2009 to 2021). "However, expression patterns of MUC2 in ovarian tumor were heterogenic." (PMID 22417007, 2012). "In this case, the appendix was normal on full microscopic examination, and the ovarian tumor expressed both CK7 and CK20, with MUC2." (PMID 34930348, 2021). "Different studies on the expression of mucins in ovarian tumors have shown overexpression of MUC1, MUC2, MUC3, MUC4, MUC5AC and MUC16 or CA125." (PMID 20034397, 2009). "Various studies have shown the overexpression of MUC1, MUC2, MUC3, MUC4, MUC5AC and MUC16 in a variety of ovarian tumors." (PMID 20034397, 2009).